NFKB2 (nuclear factor kappa B subunit 2)
Diseases named in the same sentence as NFKB2 in open-access papers (continued):
Sharing a sentence is not in itself a finding about the gene and the disease.
mastitis (2 papers, 2023 to 2025). Inflammation of breast tissue during lactation or postpartum due to an obstructed duct or infection. "In both S. aureus-positive and S. chromogenes-positive cows, the DE snoRNAs were correlated with several immune and inflammatory genes (e.g., IL1R, IL18R1, STAT3, NFKB2, MYD88, VEGFA and CD40), all of which have been reported in several studies to be associated to mastitis." (PMID 40936092, 2025). "As expected, previous data showed that NFKB1 and NFKB2 were upregulated in LPS- and LTA-induced mastitis in mammary epithelial cells, which was directly related to infection-induced inflammation during mastitis." (PMID 37620551, 2023).
osteosarcoma (2 papers, 2019 to 2024). A usually aggressive malignant bone-forming mesenchymal neoplasm, predominantly affecting adolescents and young adults. "Compared to the sham group, the SNL group had higher gene expression levels of Gadd45g (growth arrest and DNA-damage-inducible 45 gamma) and Fos (FBJ osteosarcoma oncogene), while it had lower gene expression levels of Igf1, Ccl2, Hdac2, Rtn4rl1, Nfkb2, Gpr84, Pik3cg, and Abcc8." (PMID 38790607, 2024). "In osteosarcoma cells, CDK12 could also play a role in transcriptional regulation of the MAP3K14 and NFKB2 mRNA expression, participating in activation of noncanonical NF-κB pathway." (PMID 31523177, 2019).
penile cancer (2 papers, 2022 to 2024). A primary or metastatic malignant neoplasm that affects the penis. "Furthermore, there is a high overexpression of NFKB1 mRNA in penile cancer and NFKB2 mRNA in penile lichen sclerosus, which shows an implication of the NF-kB pathway in penile cancer and some dermatoses." (PMID 39202278, 2024).
pituitary hormone deficiencies (2 papers, 2014 to 2021). "We expand the potential phenotype of such NFKB2 mutations to include additional pituitary hormone deficiencies as well as anatomical pituitary anomalies." (PMID 25524009, 2014).
acute kidney injury (1 paper, 2025). Sudden and sustained deterioration of the kidney function characterized by decreased glomerular filtration rate, increased serum creatinine or oliguria. "Further significantly upregulated transcripts related to inflammatory processes included ADAM19, PD-L1 (CD274), non-canonical NF-kB genes NFKB2 and RELB, furthermore IFITM1, JAML -linked with acute kidney injury - IRX3-linked with metabolic inflammation - and PRDM1-observed in gouty arthritis." (PMID 40281125, 2025).
Addisonian crisis (1 paper, 2022). "We report a previously healthy child with DAVID syndrome secondary to a heterozygous nonsense mutation in the NFKB2 gene presenting in Addisonian crisis associated with intracranial hypertension following ten days of non-specific symptoms of cortisol deficiency." (PMID 36494638, 2022).
adenoma (1 paper, 2015). A neoplasm arising from the epithelium. "Deletion of Nfkb2 led to a reduced tumour burden, whilst deletion of c‐Rel led to substantially increased adenoma formation." (PMID 25727407, 2015). "Adenomas from wild‐type mice had a mean Ki67+ proliferating cell index of 297 ± 20.4 cells per high power field (hpf); adenomas examined from Nfkb1−/− and Nfkb2−/− mice had similar proliferative indices." (PMID 25727407, 2015). "However, the adenomas that arose in Nfkb2−/− mice exhibited a lower apoptotic index (0.6 ± 1.8 cells per hpf, p < 0.05)." (PMID 25727407, 2015).
aging (1 paper, 2024). A developmental process that is a deterioration and loss of function over time. "Within the context of skin aging and various aging-related processes, the immune response-related genes IKBKB and NFKB2, which are integral to the NF-κB signaling pathway, play a pivotal role." (PMID 38263133, 2024).
allergic dermatitis (1 paper, 2021). "The top differentially expressed genes (DEG) between AGS subjects and controls included transcription factors regulating immune gene expression, such as the NFκB pathway (NFKBIA, NFKB2, REL), antigen presentation molecules, type 2/allergic immune responses, itch, and allergic dermatitis." (PMID 33804792, 2021).
alopecia (1 paper, 2019). Hair loss usually from the scalp. "Interestingly, trachyonychia, a distinct form of nail dystrophy observed frequently in NFKB2-mutated patients but also other diseases, is per se associated with alopecia and mild to moderate lymphocytic infiltration." (PMID 30941118, 2019).
and T cell lymphomas (1 paper, 2012). "In humans, chromosomal translocations that cause NFKB2 gene rearrangements and constitutive processing of p100 lead to B and T cell lymphomas." (PMID 22880094, 2012).
Arthritis (1 paper, 2019). Inflammation of a joint. "Only two NFKB2 mutation carriers were completely asymptomatic, one further patient suffered from late-onset arthritis as the only manifestation." (PMID 30941118, 2019).
atherosclerosis (1 paper, 2022). A disease characterized by the build-up of fatty material and calcium deposition in the arterial wall resulting in partial or complete occlusion of the arterial lumen. "In addition, NFKB2 was found to be upregulated, the p100 subunit of nuclear factor NF-kappa-B, a key regulator of inflammatory responses in the liver that drives the regulation of many genes reported to play a role in atherosclerosis development." (PMID 35897797, 2022).
autoimmune polyendocrine syndrome type 1 (1 paper, 2023). Autoimmune polyendocrinopathy type 1, or APECED syndrome, is a genetic disease that manifests in childhood or early adolescence with a combination of chronic mucocutaneous candidiasis, hypoparathyroidism and autoimmune adrenal failure. "Informative syndromes caused by errors in essential immune genes like AIRE (autoimmune polyendocrine syndrome type 1, APS-1) and NFKB2 (DAVID syndrome) causing autoimmune disease in the adrenals either as a primary or secondary, further throw light on parts of the pathogenesis of autoimmune PAI." (PMID 38027140, 2023).
B cell lymphomas (1 paper, 2016). "Rearrangements of the NFKB2 locus (gene name for the p100 subunit) that lead to loss of the inhibitory IκB-like domain and increased p52 production are found in some B cell lymphomas." (PMID 27058560, 2016).
bladder cancers (1 paper, 2016). "Although NFkB2 is a known tumor suppressor, its expression in bladder cancers has never been explored." (PMID 27095572, 2016).
bronchiectasis (1 paper, 2023). Segmental, irreversible dilation of the bronchial tree resulting in the accumulation of secretions which leads to obstruction. "The patient with the NFKB2 mutation had bronchiectasis, splenomegaly, and recurrent HSV-1 reactivation." (PMID 37511905, 2023).
Cerebral ischemia (1 paper, 2023). Restriction of arterial blood supply to the brain associated with insufficient oxygenation to support the metabolic requirements of the tissue. "In addition, DHQ decreased the activity of myeloperoxidase, brain mRNA levels of interleukins, and Nfkb2 in cerebral ischemia/reperfusion in rats, thus inhibiting inflammation." (PMID 37886968, 2023).
chronic GvHD (1 paper, 2020). "Here we report studies of a patient with chronic GvHD (cGvHD) carrying persistent CD4+ T cell clonal expansion harboring somatic mTOR, NFKB2, and TLR2 mutations." (PMID 32382059, 2020).
colonic adenoma (1 paper, 2015). "Collectively, these observations demonstrate that deletion of c‐Rel and Nfkb2 has inverse effects on colonic adenoma development following DSS/AOM." (PMID 25727407, 2015).
depression (1 paper, 2024). "Five of these TFs, namely ETS1, TFAP2A, NFKB2, CTCF, and RELA, are significantly deregulated in the blood samples of depression patients compared to controls (GSE217811 and GSE23848)." (PMID 38256187, 2024).
Epstein-Barr virus infection (1 paper, 2021). An infection that is caused by Epstein-Barr virus. "One was the Epstein-Barr virus infection pathway (q-value=0.025), represented by four upregulated genes (CDKN1A, NFKB2, RELB, and PDIA3) and two downregulated genes (BID and HLA-A)." (PMID 33785040, 2021).
gastric adenocarcinoma (1 paper, 2024). "The GEPIA website online analysis of NFKB2 gene differential expression levels showed that the NFKB2 gene was significantly upregulated in gastric adenocarcinoma tissues (P<0.05)." (PMID 38577985, 2024).
giardiasis (1 paper, 2022). An infection of the small intestine caused by the flagellated protozoan giardia lamblia. "In patients with a mutation in NFKB2, giardiasis has been described previously, as well as gastrointestinal NLH, which was also seen in our NFKB2-patient, though without infection." (PMID 34599484, 2022).
hepatoma (1 paper, 2017). "Our results also validate recent results observed in a hepatoma cell lines resistant to Sorafenib, where it was proposed that resistance to the drug treatment was associated with high CD47 protein levels achieved by the binding of NFKB2 subunit to the CD47 promoter upon TNF-α stimulation." (PMID 28378740, 2017).
Hodgkins lymphoma (1 paper, 2024). A heterogeneous group of malignant lymphoid neoplasms of B-cell origin characterized histologically by the presence of Hodgkin and Reed-Sternberg (HRS) cells in the vast majority of cases. "A few years ago, ChIP-seq experiments on Hodgkin lymphoma cells identified 10,893 DNA-binding regions for NFKB2 p52, within or in the close vicinity of 5,497 genes." (PMID 39607428, 2024).
Hyperglycemia (1 paper, 2021). An increased concentration of glucose in the blood. "In this study, hyperglycemia-induced cone-specific expression of NF-κB family members, including REL, RELA, and NFKB2." (PMID 34434927, 2021).
hypophosphatemic rickets (1 paper, 2024). Rickets due to low serum phosphate concentrations, the cause of which can be nutritional or genetic. "For example, patients with pathogenic variants in NFKB2 or IGSF1 or the dual diagnosis of patient 37 (neurofibromatosis and hypophosphatemic rickets) would have been missed by targeted panel sequencing." (PMID 37940764, 2024).
lung adenocarcinoma (1 paper, 2018). A carcinoma that arises from the lung and is characterized by the presence of malignant glandular epithelial cells. "Higher p100/p52 (Nfkb2) expression in lung adenocarcinomas correlated with reduced patient survival (p = 3 × 10−7)." (PMID 29666445, 2018).
lung disease (1 paper, 2023). "Of those with significant lung disease, 12 subjects had a TACI variant, 4 had NFKB2, 4 had NFKB1 and 3 others had PI3KCD variants." (PMID 38274105, 2023).
malaria (1 paper, 2020). Malaria is a serious and sometimes fatal disease caused by a parasite that commonly infects a certain type of mosquito which feeds on humans. "Global analysis of the BAFF-var allele on total RNA expression revealed many differentially expressed genes implicated in the immune response to malaria; among them, we selected CXCL10, CR1, MIF, ICAM-1, and NFKB2 for further analysis." (PMID 33123155, 2020). "B cells expressed higher levels of NFkB2 mRNA in response to P. falciparum antigens in iRBC-var relative to all other groups (uRBC-WT, uRBC-var, and iRBC-WT), suggesting a role for BAFF-var in regulating NFKB2 levels in B cells treated with malaria antigens." (PMID 33123155, 2020).
meningioma (1 paper, 2020). A generally slow growing tumor attached to the dura mater. "All of these findings led us to investigate the association of hypoxia, in addition to RELB, pSTAT3 and NFKB2 expressions with PD-L1 expression in our meningioma cohort." (PMID 32839486, 2020). "We found a link between high PD-L1 and NFKB2 expressions in meningiomas specially in high grade tumors." (PMID 32839486, 2020). "Of note, we detected cytoplasmic NFKB2 immunoreactivity in all grades of meningioma with a more diffuse pattern in high-grade cases (Grades II and III)." (PMID 32839486, 2020). "Furthermore, our study hypothesized a link between NFKB2, hypoxia and PD-L1 expression in meningioma." (PMID 32839486, 2020). "We observed high expression of NFKB2, RELB, pSTAT3, and positive CA9 expression in 30% (26/88), 26% (24/91), 63% (46/73), and 51% (37/72) of the meningioma cases, respectively." (PMID 32839486, 2020). "We then categorized the meningiomas cases based on co-expression of all three markers: PD-L1 (high/low, median = 0.08%), NFKB2 (high/low), and CA9 (positive/negative) into 8 subgroups." (PMID 32839486, 2020). "We then evaluated the expression of specific candidate proteins: NFKB2, pSTAT3, RELB, and CA9 by immunohistochemistry based on availability of the unstained slides and we correlated their expression with that of PD-L1 in our meningioma cohort." (PMID 32839486, 2020).
nasopharyngeal carcinoma (1 paper, 2025). A carcinoma arising from the nasopharyngeal epithelium. "In nasopharyngeal carcinoma (NPC), the transcription of CD70 was found to be activated by NFKB2 upon infection with Epstein–Barr virus." (PMID 40629902, 2025).
Opportunistic infection (1 paper, 2015). An infection that is caused by a pathogen that would generally not be able to cause an infection in a host with a normal immune system. "This is likely to be due to the susceptibility of NFκB2 deficient mice to opportunistic infections because both Tnf-/-Nfkb2-/- and Traf2EKO/EKONfkb2-/- mice also succumbed to such infections and." (PMID 26701909, 2015).
pancreatic cancer (1 paper, 2017). "For instance, NFKB2 (described in more detail the next section) is important for gemcitabine sensitization: inhibiting NFKB2 increases the gemcitabine cytotoxicity in pancreatic cancer cell lines BxPC2, Capan1 and PancTu1." (PMID 29023490, 2017).
Pleural effusion (1 paper, 2008). The presence of an excessive amount of fluid in the pleural cavity. "In addition, a trend towards significance was found for association of the NF-κB pathway related genes IL1B and NFKB1 with the occurrence of severe complications and for IL8 and NFKB2 with pleural effusion." (PMID 18398488, 2008).
pneumococcal infection (1 paper, 2019). Infections with bacteria of the species streptococcus pneumoniae. "Consequently, we examined whether Zn deficiency dysregulated this inflammatory axis in the context of pneumococcal infection by assessing transcription of nfkb-1 (p105 subunit) and nfkb-2 (p100 subunit)." (PMID 31437249, 2019).
renal carcinoma (1 paper, 2024). A carcinoma arising from the epithelium of the renal parenchyma or the renal pelvis. "Moreover, patients with high NFKB2 expression in grade 3 renal carcinoma died significantly earlier than those with a low expression." (PMID 39062057, 2024). "Interestingly, the female patients with renal carcinoma had significantly longer survival times compared with males if NFKB2 mRNA expression was low." (PMID 39062057, 2024). "Similarly, patients with low neoantigen load and low NFKB2 mRNA expression in their renal carcinoma cell type had a better survival prognosis than those with high NFKB2 expression and a significantly higher survival time than the patients with a low mutational rate." (PMID 39062057, 2024).
Salmonella Infections (1 paper, 2023). Infections with bacteria of the genus SALMONELLA. "Furthermore, the expression of genes in the PURA regulon were upregulated upon Salmonella infection to a similar extent as the genes in the NFKB2 regulon, which is a known pro‐inflammatory TF." (PMID 37073532, 2023).
serous ovarian cancer (1 paper, 2021). "What is interesting is that the ratio of NFKB1 to NFKB2 expression levels significantly decreased in high-grade serous ovarian cancer cells after incubation with all tested peptides." (PMID 35008474, 2021).
tendinitis (1 paper, 2022). Inflammation of a tendon, usually resulting from an overuse injury. "LlncRNA-COL6A4P2, A2MP1 and LOC100996671 may regulate the inflammation of LHBT in RCT patients through NFKB2/NF-kappa B signaling pathway, and preliminarily revealed the pathological molecular mechanism of tendinitis of LHBT." (PMID 35725478, 2022).
Toxoplasma encephalitis (1 paper, 2019). "A direct role for Nfkb2 in the immune response against T. gondii has been described in the Nfkb2−/− mouse model, in which severe Toxoplasma encephalitis develops." (PMID 31506064, 2019).
trachyonychia (1 paper, 2019). "Therefore, trachyonychia may facilitate another T cell mediated form of an autoimmune manifestation in NFKB2-mutated patients." (PMID 30941118, 2019).
yang deficiency (1 paper, 2022). Yang deficiency is a concept from traditional Chinese medicine. "In particular, KAT2B, NFKB2, CREBBP, and GTF2H3 were the key contributive targets for the Yang deficiency group." (PMID 35341155, 2022). "The symptomatic gene targets for Yang deficiency (KAT2B, NFKB2, CREBBP, GTF2H3) or Yin deficiency (JUNB, JUND, NGLY1, TNF, RAF1, PPP1R15A) were potentially discovered." (PMID 35341155, 2022). "KAT2B, NFKB2, CREBBP, and GTF2H3 are represented as candidate markers for Yang deficiency." (PMID 35341155, 2022).